KRT10 (keratin 10)
Diseases named in the same sentence as KRT10 in open-access papers (continued):
Sharing a sentence is not in itself a finding about the gene and the disease.
cervical carcinoma (4 papers, 2011 to 2025). A carcinoma arising from either the exocervical squamous epithelium or the endocervical glandular epithelium. "Thus, it is suggested that KRT1 and KRT10 are involved in the proliferation of cervical keratinocytes in cervical cancer." (PMID 36765810, 2023). "In cervical cancer, KRT1 (type II; “acidic” keratin) and KRT10 (type I; “basic” keratin) are upregulated in cervical cancer." (PMID 36765810, 2023).
Palmoplantar keratoderma (4 papers, 2018 to 2023). Abnormal thickening of the skin of the palms of the hands and the soles of the feet. "Thus, deficiencies in KRT10 likely do not manifest as palmoplantar keratoderma because, at acral sites, KRT9 is the main binding partner of KRT1." (PMID 35900871, 2022). "Interestingly, KRT1-associated EHK has an accompanying palmoplantar keratoderma that is generally absent in KRT10-associated EHK." (PMID 35900871, 2022). "For instance, for hystrix ichthyoses, it has been postulated that mutations in KRT1 result in a phenotype with the presence of palmoplantar keratoderma, the IH-CM type, while mutations in KRT10 cause the Lambert type (IH-L), in which palmoplantar keratoderma is absent." (PMID 29689068, 2018).
pterygium (4 papers, 2021 to 2024). A wedge-shaped fibrovascular lesion arising from the bulbar conjunctiva and extending to the cornea. "The SVM algorithm was also employed to rigorously select hub genes associated with pterygium, revealing five significant genes: KRT10, KRT6B, BTG2, ASPG and NGEF." (PMID 39722894, 2024). "We conducted a rigorous screening process and identified KRT10 and NGEF as crucial genes implicated in the pathogenesis of pterygium." (PMID 39722894, 2024). "The identification of pivotal feature gene KRT10 and NGEF provide valuable insights into the molecular mechanisms underlying pterygium progression." (PMID 39722894, 2024). "Notably, KRT10 and NGEF were consistently identified as hub genes associated with pterygium across all two machine learning methods and WGCNA." (PMID 39722894, 2024). "Using WGCNA, RF, and SVM, we identified KRT10 and NGEF as pivotal feature genes influencing pterygium progression." (PMID 39722894, 2024). "The remaining drug candidates exhibited interactions with KRT10 and NGEF, offering valuable insights for the advancement of pterygium treatment research and development." (PMID 39722894, 2024). "In our analysis of RNA-Seq data derived from 68 samples, we observed a statistically significant elevation in the expression levels of KRT10 and NGEF genes in the pterygium group compared to the bulbar conjunctiva group, with a P-value <0.05." (PMID 39722894, 2024). "The discovery of pivotal genes, namely, KRT10 and NGEF, coupled with insights into immune cell infiltration patterns and pertinent signaling pathways, establishes a foundation for future research endeavors aimed at deciphering the pathophysiology of pterygium." (PMID 39722894, 2024). "qPCR analysis confirmed the elevated expression of KRT10 and NGEF in pterygium tissues." (PMID 39722894, 2024). "In our study, we found only minimal changes, with modest upregulation of KRT10 in pterygium and no expression of KRT1 in either pterygium or pinguecula; in addition, FLG2 was modestly upregulated in pinguecula." (PMID 34769520, 2021).
adenosquamous carcinoma (3 papers, 2004 to 2021). A carcinoma composed of malignant glandular cells and malignant squamous cells. "Finally, only adenosquamous carcinoma tumors from both Cre- and Cre+ mice labelled positively for the skin marker keratin 10 typical of the epidermoid differentiation of these tumors (Figure 5Aix)." (PMID 26439696, 2015). "Since the pathological tumor tissue was adenosquamous carcinoma, we observed several keratins, including KRT1, KRT6B, KRTDAP, and KRT10, in C5." (PMID 34326696, 2021).
dermatitis (3 papers, 2014 to 2024). An inflammatory process affecting the skin. "Further, COX–2, Keratin 10, and apoptosis were changed for the progression of dermatitis, epidermal hyperplasia, and irradiated skin damage." (PMID 39272290, 2024).
cholesteatoma (2 papers, 2018 to 2021). A pathologic process characterized by the proliferation of keratinizing squamous epithelium resulting in the accumulation of keratin and cells in the middle ear and/or mastoid. "The differences in the expression pattern of the KRT1 and KRT10 genes observed in our study support the hypothesis that distinctly altered cellular differentiation processes are associated with cholesteatoma formation in pediatric and adult cases." (PMID 30021014, 2018). "In our cholesteatoma samples KRT1 and KRT10 showed identical expression patterns as it was expected, since they protein products are known to form heteroduplex in cells." (PMID 30021014, 2018). "Based on our results it can be concluded that the expression pattern of KRT1, KRT10 and KRT19 genes seen in our pediatric cholesteatoma samples suggests elevated immature keratinocyte differentiation and elevated proliferation potential, especially in recurrent samples." (PMID 30021014, 2018).
colorectal cancer (2 papers, 2019 to 2020). A primary or metastatic malignant neoplasm that affects the colon or rectum. "Studies have shown that KRT10 protein has differential expression profiles in tissues or cells, including lung and colorectal cancers, epidermolysis palmoplantar keratoderma lesions, and coronary heart disease." (PMID 31159303, 2019).
Hyperglycemia (2 papers, 2016 to 2023). An increased concentration of glucose in the blood. "The initiation of EMT in HaCaT cells from hyperglycemia was confirmed by a morphological change, the increased expression of CDH2, KRT10, and ACTA2, and the downregulation of CDH1." (PMID 36827547, 2023).
keloid (2 papers, 2022 to 2023). An irregularly shaped, elevated mark on the skin caused by deposits of excessive amounts of collagen during wound healing. "Most keratins were downregulated in keloids, including KRT10, KRT14, KRT15, KRT19, KRT1, KRT77, and KRT5." (PMID 35435317, 2022). "Most keratins and cell junction related proteins such as KRT10, EVPL, PPL, and DSP were downregulated in keloids." (PMID 35435317, 2022).
lung carcinoma (2 papers, 2022 to 2023). "KRT6B and KRT10 were found to be abundant in exhaled breath condensate and to be potential biomarkers for the early diagnosis of lung cancer." (PMID 35512017, 2022). "KRT8 was used for cancer prognosis, including for ADC patients, whereas KRT10 was found to be a useful biomarker for the treatment response in lung cancer." (PMID 35512017, 2022).
Olmsted syndrome (2 papers, 2012 to 2025). A hereditary palmoplantar keratoderma characterized by the combination of bilateral mutilating transgredient palmoplantar keratoderma and periorificial keratotic plaques. "Normally cytokeratin 10 is confined to the suprabasal layers whereas this cytokeratin 10 stained only the upper layer of the epidermis in hyperkeratotic lesions of Olmsted syndrome." (PMID 23320205, 2012).
oral cancer (2 papers, 2022 to 2023). "Previous studies have linked altered KRT10 expression to the dysplastic progression of oral cancer." (PMID 36393868, 2022). "Some of the DEGs common to OLP and oral cancer include KRT4 (down-regulated) and KRT16, KRT17, KRT10, and KRT75 (up-regulated)." (PMID 38234400, 2023).
periodontitis (2 papers, 2023 to 2025). An acute or chronic inflammatory process that affects the tissues that surround and support the teeth. "Genes related to keratinocyte differentiation and the epidermal differentiation complex, including keratin family members (KRT1, KRT2, and KRT10) and loricrin (LOR), were also among the most downregulated genes in periodontitis." (PMID 41124422, 2025). "The SPAG4, CCDC69, KRT10, CXCL12, HPGD, CLDN20 and CCL187 genes were the most important cross-talk genes between periodontitis and IgAN." (PMID 36793719, 2023). "By taking the intersection of WGCNA important module genes and DEGs, we found that the SPAG4, CCDC69, KRT10, CXCL12, HPGD, CLDN20 and CCL187 genes were the most important cross-talk genes between periodontitis and IgAN." (PMID 36793719, 2023). "By taking the intersection of WGCNA important module genes and DEGs, we found that the SPAG4, CCDC69, KRT10, CXCL12, HPGD, CLDN20 and CCL187 genes were the most important cross-talk genes between periodontitis and IgAN, and these genes may be related to kinase regulator activity." (PMID 36793719, 2023).
Stevens-Johnson syndrome (2 papers, 2013 to 2020). Stevens-Johnson syndrome is a limited form of toxic epidermal necrolysis characterized by destruction and detachment of the skin epithelium and mucous membranes involving less than 10% of the body surface area. "KRT10 expression is associated with ocular surface diseases like Stevens Johnson syndrome and superior limbic keratoconjunctivitis, and KRT1/KRT10 are not expressed in healthy conjunctival tissue." (PMID 32929145, 2020).
adenoma (1 paper, 2024). A neoplasm arising from the epithelium. "In addition to our proposed markers, KRT1, KRT2, and KRT10 were enriched in the C group among the stromal CDX2- population in our previous DVP experiment, consistent with the intensity increase observed in our larger adenoma cohort." (PMID 39252972, 2024).
atherosclerosis (1 paper, 2021). A disease characterized by the build-up of fatty material and calcium deposition in the arterial wall resulting in partial or complete occlusion of the arterial lumen. "Multivariate logistic regression showed that KRT10 was significantly related to atherosclerosis in SLE patients (p < 0.05)." (PMID 33936038, 2021). "Further investigations are required to clarify whether KRT10 is a driver or simply a marker for atherosclerosis." (PMID 33936038, 2021). "The present data suggest that KRT10 may play a role in the atherosclerosis in SLE." (PMID 33936038, 2021). "Finally, the study had a cross-sectional design, and thus the causal relationships between DE genes like KRT10 and atherosclerosis could not be determined." (PMID 33936038, 2021). "A previous study showed that increased expressions of cytokeratin 8, 18, and 19 were related to increased arterial intimal thickening features in atherosclerosis, while a link between KRT10 and atherosclerosis has not been reported." (PMID 33936038, 2021).
colon adenoma (1 paper, 2012). An adenoma that arises from the colon. "Indeed, increasing Igf2 levels through LOI (heterozygous deletion of H19) or with a keratin 10 promoter increases the number and size of colon adenomas as well as malignant progression in APCMin/+ mice." (PMID 22952916, 2012).
dermatophytosis (1 paper, 2025). A common fungal infection of the stratum corneum of the skin, hair, or nails by a dermatophyte. "In this case, the siblings developed dermatophytosis in addition to KRT10-mutant BCIE, while their cohabiting parents remained unaffected." (PMID 40868266, 2025).
eczema (1 paper, 2022). "The ability of S. aureus Newman to adhere to loricrin and cytokeratin 10 is crucial for colonization of the nares of carriers and the skin of eczema patients." (PMID 35647689, 2022).
endometriosis (1 paper, 2023). The growth of functional endometrial tissue in anatomic sites outside the uterine body. "FOXJ1+ ciliated cells and LGR5+ and SOX9+ cells were found to be surrounded by KRT10 (keratin 10)+ cells both within and outside of the endometriosis lesion proper." (PMID 37353907, 2023).
Fibroadenoma (1 paper, 2020). A benign tumor of the breast characterized by the presence of stromal and epithelial elements. "Furthermore, the expression of seven step-changing proteins (KRT10, KRT1, KRT6E, PLIN1, HBA2, FHL1, and ME2) were decreased in fibroadenoma tissues compared to fibroadenoma adjacent and normal tissues." (PMID 33194682, 2020). "For fibroadenoma tissues, compared with both fibroadenoma-adjacent and normal tissues, there were six up-regulated (ANXA6, VCP, SERPINH1, galactosidase alpha, NNT, and MMP11) and 38 down-regulated (KRT10, KRT1, ALDH1A1, ECM1, and others) proteins in fibroadenoma." (PMID 33194682, 2020).
ichthyosis hystrix (1 paper, 2018). "Here, we have genetically and structurally analysed the effect of a novel mutation in KRT10 identified in a patient affected by a sporadic form of hystrix ichthyosis of Curth-Macklin." (PMID 29689068, 2018). "The result of this current work now demonstrates that ichthyosis hystrix of Curt Macklin is associated to both KRT1 and KRT10 mutations, when they lead to the disruption of the correct 2B-V2 hetero-domain, linking the disease to the loss of function of this structure." (PMID 29689068, 2018).
inflammatory bowel disease (1 paper, 2023). A spectrum of small and large bowel inflammatory diseases of unknown etiology. "According to research, KRT10 (keratin type I cytoskeletal protein 10) increases in people with inflammatory bowel disease and physically alters and rearranges the structure of the gastrointestinal tract's epithelial cells." (PMID 37169818, 2023).
Insulin resistance (1 paper, 2019). Increased resistance towards insulin, that is, diminished effectiveness of insulin in reducing blood glucose levels. "Similarly, inhibition of insulin signaling decreased KRT5 and KRT10 protein levels, indicating that expression of these molecules is directly influenced by insulin resistance." (PMID 31581253, 2019).
pertussis (1 paper, 2023). A contagious bacterial respiratory infection caused by Bordetella pertussis. "We also predicted the most effective cores for siRNAs to affect staphylococcus aureus (ClfB, IsdA, sdrC, sdrD, and SasG) and pertussis (PtxE, PagP, PtxD, PtxC, PtxA, and PtxB) bacterial genes that interacted with human KRT10, FGG, and TLR4 genes." (PMID 37169818, 2023). "In this study, five important human genes (KRT10, FGG, TLR4, CD14, and MD2) reported in the development and spread of pertussis and staphylococcus aureus infections." (PMID 37169818, 2023).
pneumococcal pneumonia (1 paper, 2022). A febrile disease caused by STREPTOCOCCUS PNEUMONIAE. "Keratin-10 as a ligand is elevated in cellular senescence of lung cells and these keratin-10/PsrP interactions have been linked to increased susceptibility to pneumococcal pneumonia in the elderly." (PMID 35646747, 2022).
scleroderma (1 paper, 2022). Scleroderma is a rare autoimmune connective tissue disorder characterized by abnormal hardening of the skin and, sometimes, other organs. "Immunofluorescence stainings revealed that the expression levels of epidermal stem cell markers (KRT14 and TP63) and mature epidermal marker (KRT10) were downregulated in scleroderma, while these proteins were recovered to normal levels in the treatment group." (PMID 35315234, 2022).
skin squamous cell carcinoma (1 paper, 2020). A carcinoma arising from the squamous cells of the epidermis. "A previous study showed that both EGFR small interfering RNA (siRNA) and EGFR inhibitors increase the expression of several differentiation markers, including keratin 1, keratin 10, and involucrin in primary human keratinocytes, intact epidermis, and skin squamous cell carcinomas." (PMID 33096942, 2020).
staphylococcal infection (1 paper, 2012). An infection caused by Staphylococcus. "S. aureus binds to mouse cytokeratin 10, and antibody to ClfB impairs nasal colonization, which can diminish the risk of staphylococcal infection." (PMID 23077517, 2012).
tumor (50 papers, 2004 to 2025). "The Krt10 gene was one of the genes in which multiple integrations were identified in MmuPV1-induced tumor tissues by both RNA-seq and RACE-SMRT-seq." (PMID 34343212, 2021). "We also analyzed the expression of Krt10 and Fabp5, two highly expressed genes that had multiple MmuPV1 integration sites in tumor tissues and performed RNA ISH using RNAscope technology." (PMID 34343212, 2021). "They contained typical horn pearls, rarely displayed surface ulcerations and the tumor cells expressed keratin 5 (Krt5) and β4-integrin (Itgb4) in basal layers, and keratin 10 (Krt10) in upper layers when present." (PMID 31803622, 2019). "Filaggrin and keratin 10 expression in the tumor center of SCC was also significantly higher than in the tumor center of BCC (5.50±2.98, p<0.05; 0.39±0.09, p<0.001)." (PMID 22808251, 2012). "For example, cutaneous SCC typically retains characteristics of squamous differentiation, and we found elevated filaggrin and keratin 10 gene expression in the SCC tissue of the tumor center." (PMID 22808251, 2012). "Filaggrin and keratin 10 expression in the tumor center was also higher compared to the tumor margin (0.44±0.22, p<0.001; 1.56±0.51, p<0.05) and to peritumoral tissue (0.62±0.18, p<0.001; 1.19±0.34, p<0.01)." (PMID 22808251, 2012). "However, by using RNA ISH (RNAscope technology), we showed that there was reduced expression of Krt10 and Fabp5 in MmuPV1 tumor tissues." (PMID 34343212, 2021). "Furthermore, keratin 10 knock-out mice displayed reduced tumor formation in a 2-stage skin carcinogenesis model, possibly caused by an accelerated turnover of keratinocytes due to activation of MAPK pathways." (PMID 23536778, 2013). "However, administration of EA and BU extracts significantly decreased the number and size of cytokeratin 10/13-positive tumor cells, suggesting that the extracts may have potency for reducing hepatic and pulmonary metastasis of epidermal SCC." (PMID 27293462, 2016). "Proteomic analysis of serum samples from PDAC patients with well‐characterized tumor subtypes revealed that several keratins, including KRT2, KRT5, KRT10, and KRT77, were highly abundant in samples from patients with basal‐like tumors." (PMID 39478658, 2025). "In pt #003, KRT10 and KRT13 were detected within the central cells of the organoid, consistent with expression in the matched patient tumor tissue section." (PMID 40624315, 2025). "This presents a convenient test case for SpatialCorr and we indeed identified strong correlation between expected type 1 and type 2 pairs such as KRT1 and KRT10, as well as KRT5 and KRT14, throughout the epidermis and much of the tumor." (PMID 36590683, 2022). "Cytokeratin 10/13 is highly expressed in SCC cells, including SAS cells, and immunohistochemistry for cytokeratin 10/13 is indicative of metastasis of tumor cells in liver and lung." (PMID 27293462, 2016). "Remarkably, individual cells of SC-driven tumours co-expressed marker molecules for both SG (adipophilin/SCD1) and squamous differentiation (keratin 10)." (PMID 25608467, 2015). "Samples within the central tumor tissue of SCC showed significantly elevated mRNA expression of filaggrin (13.60±4.52-fold (mean ± SEM), p<0.05) and keratin 10 (10.83±0.51-fold, p<0.001) compared to normal skin." (PMID 22808251, 2012). "In well to moderately differentiated tumor samples with low level of CTIP2 expression, Cytokeratin 10 was expressed in clusters." (PMID 19399189, 2009). "Furthermore, temporal variation in keratin expression differed between normal and tumor cells, with KRT10 highly expressed exclusively during normal epithelial differentiation, while KRT17 was highly expressed throughout tumor progression." (PMID 40470730, 2025). "Besides the differential expression of KRT5 and KRT19 between the margin and tumor center, KRT6B, KRT8, KRT10, and KRT17 were identified among the proteins differentiating the cancer from control tissue." (PMID 35512017, 2022).